NF1 (neurofibromin 1)
Diseases named in the same sentence as NF1 in open-access papers (continued):
Sharing a sentence is not in itself a finding about the gene and the disease.
glioma (continued). "We identified anti-proliferative and pro-migratory roles for miR-9, which can also target NF1, in glioma cells." (PMID 23185366, 2012). "In our study, we identified NF1, a well-known glioma suppressor, as a functional target of miR-9 in the regulation of glioma cell migration." (PMID 23185366, 2012). "While at least 15% of patients with NF-1 developoptic pathway gliomas, approximately one-third of patients with optic pathway gliomasare subsequently found to have NF-1." (PMID 21603196, 2011). "Our finding of MIA expression in various NF1-related tumours is consistent with the findings of previous reports that MIA is expressed in glial tumours." (PMID 21726432, 2011). "There is increasing evidence that the NF-1 gene is involved in the tumorigenesis of not only NF-1-related but also sporadically occurring gliomas." (PMID 24212955, 2011). "Optic gliomas inassociation with NF-1 seem to contribute to precocious puberty through direct masseffect." (PMID 21603196, 2011). "As expected in this supervised approach, three-way clustering was the best fit and all but three glioma samples showed stable clustering into signaling classes associated with EGFR, PDGF and NF1-loss." (PMID 19915670, 2009). "As routine screening for gliomas is a part of care of patients with NF-1, it is suggested that screening for lung cancer in this population should be a routine." (PMID 20531996, 2009). "However, we excluded children with NF1 with moyamoya, glioma, or who had received chemotherapy to limit our sample to children without visible white matter injury or other significant brain abnormalities." (PMID 40270760, 2025). "In particular, as both copies of NF1 in the glioma were already inactivated, there should be no selection pressure for further loss-of-function mutations in NF1 in tumor cells." (PMID 40000831, 2025). "Nf1 mutations cause baseline hyperexcitability via the regulatory mechanism of HCN1 channels, and the antiepileptic medication lamotrigine can target this channel, normalizing midkinase expression and reducing glioma proliferation." (PMID 40092993, 2025). "This highlights that while biopsy may be necessary in atypical or unclear cases, it is not routinely required when imaging strongly suggests low-grade glioma, particularly in the context of NF1." (PMID 41440192, 2025). "Through dividing the samples into high and low SASP Score groups using the median SASP Score as a threshold, we observed more EGFR (26.67%), PTEN (27.14%), and NF1 (10%) mutations in the high SASP Score group than low SASP Score group (EGFR (1.90%), PTEN (0.95%), NF1 (4.76%)) of glioma." (PMID 40781221, 2025). "Molecular genetic AI-based tumor classifiers are already in everyday use, but are not explicitly established for NF1-associated glial tumors." (PMID 41168866, 2025). "It is necessary to discover the pathomechanism of this phenomenon, which in the future could be the basis for finding drugs with protective properties in relation to the formation of gliomas in patients with NF1." (PMID 40361331, 2025). "TERT promoter mutations or EGFR amplification have not yet been described in the setting of NF1-associated gliomas, while alteration as a gain of chromosome 7 and loss of 10 were rarely observed." (PMID 40277798, 2025).
glioma (continued). "Individuals with NF1 can also develop neoplasias including optic nerve gliomas, pilocytic astrocytomas, juvenile myelomonocytic leukemia, gastrointestinal stromal tumors and both low- and high-grade gliomas." (PMID 39016685, 2024). "About 15–20% of NF1 patients develop glioma, the majority of which comprise of LGG (~17%)." (PMID 36730269, 2023). "Moreover, it should be considered that nearly 50% of patients with NF-1 who received RT during childhood subsequently developed brain tumors secondary to RT, often high-grade gliomas, which are characterized by a very poor prognosis." (PMID 37830595, 2023). "By comparing the top 20 genes with highest frequency of somatic mutations in low- (n=441) and high-risk (n=203) group, we found that higher frequency of IDH, ATRX, and CIC mutations in gliomas with low LRS risk, while mutations of EGFR, PTEN, and NF1 were more frequent in the high-risk group." (PMID 36860853, 2023). "Furthermore, our analysis revealed that NF1, PIK3R1 and PIK3CA are commonly mutated genes in H3F3A-mutant gliomas (24.6%, 17.7%, and 7.7%, respectively)." (PMID 37524847, 2023). "The study also has implications for radiation treatments in other tumor predisposition syndromes, beyond NF1 where a high-risk of MPNST and high-grade glioma is already known after childhood irradiation, and especially for SMARCB1-related-schwannomatosis in which MPNST is already reported." (PMID 37051330, 2023). "Subsequent research demonstrated that NF1 mutation resulted in higher expression of the cytokine Midkine that activated CD8+ T-cells, which then produced Ccl4, a cytokine that induced microglia to express Ccl5 necessary for glioma growth and formation." (PMID 38318325, 2023). "In addition, previous studies have revealed cell subtypes that are associated with glioma progression, and EGFR, NF1, and PDGFRA/IDH1 are markers for the classical, mesenchymal, and proneural types, respectively." (PMID 37371484, 2023). "Approximately 35–50% of the cellular composition of NF-1-associated gliomas consists of non-neoplastic stromal cells, mainly microglia, which are a population of monocytes residing in the CNS." (PMID 37830595, 2023). "The transplantation of these o-GSCs into the brainstems of 3-week-old NF1+/- mice yielded optic gliomas within 6 months, but not transplantation of o-GSCs into brainstems of immunocompromised athymic mice, emphasizing the need for NF1+/- local microenvironment in glioma formation." (PMID 38318325, 2023). "None of the 47 NF1-associated gliomas in this cohort had IDH1 or IDH2 mutation, EGFR amplification, TERT promoter mutation, or histone H3 p.G34 mutation." (PMID 35945463, 2022). "These epigenetic results are similar to a recent study that found most NF1-associated low-grade gliomas did not cluster together with the three reference classes of sporadic pilocytic astrocytomas (supratentorial, midline, and posterior fossa)." (PMID 35945463, 2022). "While children with NF1 generally harbor low-grade gliomas, which are considered less aggressive, adults with the same syndrome may develop malignant gliomas." (PMID 35053664, 2022). "In addition, NF1 mutant-associated and sporadic astrocytoma, as well as the activations of RAF/MEK/MAPK and PI3K/AKT signaling pathways were determined in glioma patients." (PMID 36483593, 2022). "Since T cells present in human PAs and Nf1 murine low-grade gliomas establish a supportive microenvironment for low-grade glioma growth in vivo, it is important to use host systems with immune systems with limited immunologic impairment, such as Cxcl10−/− mice." (PMID 35986378, 2022). "Gliomas in NF-1 have also been reported in the cortex, cerebellum, and basal ganglia." (PMID 36010360, 2022).
glioma (continued). "It created the loss-of-function alleles of nf1a and nf1b, NF1 orthologues in zebrafish, which accelerated the tumour onset and increased the penetrance of high-grade gliomas and malignant peripheral nerve sheath tumours (MPNSTs), indicating the tumour suppressive role of nf1 in zebrafish." (PMID 36077320, 2022). "In our longitudinal analysis of three paired initial and recurrent or metastatic high-grade gliomas, the key genetic drivers (e.g., NF1, CDKN2A, ATRX) were shared truncal events while only chromosomal copy number aberrations were private to initial or recurrent/metastatic tumors." (PMID 35945463, 2022). "Whether the high-grade gliomas arising in the setting of NF1 occur de novo or from transformation of a pre-existing low-grade glioma following acquisition of additional oncogenic drivers (e.g., CDKN2A deletion, ATRX mutation) remains uncertain." (PMID 35945463, 2022). "This suggests that glioma initiation may occur prior to biallelic NF1 inactivation in some patients, with the somatic events targeting the remaining wildtype NF1 allele occurring within different tumor subclones later during gliomagenesis." (PMID 35945463, 2022). "NF1 is also a recognized risk factor for the development of malignancy particularly malignant peripheral nerve sheath tumors (MPNST), optic gliomas, other gliomas, and leukemia." (PMID 36321000, 2022). "Conversely, patients with NF1 carrying large heterozygous deletions involving NF1 and contiguous genes lying in its flanking regions are tall, although some patients with NF1 and tall stature (>90th percentile) could have a central nervous system tumor." (PMID 35456261, 2022). "Schematic model of NF1-MAPK-FOSL1 axis in mesenchymal (MES) gliomas." (PMID 34399888, 2021). "(C) FOSL1 mRNA expression in IDH-wt gliomas, stratified according to NF1 alterations." (PMID 34399888, 2021). "In conclusion NF experts and patient representatives consent to prioritise the development of future clinical trials for new drug treatments for MPNST, benign peripheral nerve sheath tumours, cutaneous manifestations and high grade gliomas for NF1; tumour manifestations for NF2; and pain for SWN." (PMID 33903738, 2021). "NF1 is one of the most common heritable brain tumor predisposition disorders, in which affected individuals develop low-grade gliomas classified as WHO grade I gliomas (pilocytic astrocytomas)." (PMID 33530415, 2021). "Therefore, the distribution of GBM patients with NF1 was unclear which differs from low-grade glioma patients." (PMID 33787635, 2021). "Gliomas of the mesenchymal subtype are defined by high expression of chitinase 3-like 1 and MET5, as well as a high frequency of neurofibromatosis type 1 (NF1) mutation/deletion and low levels of NF1 mRNA." (PMID 34603399, 2021). "Similarly, trametinib has shown a reduction in tumor volume in recurrent pediatric low-grade gliomas and NF1-driven plexiform neurofibromas." (PMID 33580196, 2021). "(D) Correlation of FOSL1 and NF1 mRNA expression in IDH-wt gliomas." (PMID 34399888, 2021). "This suggests that among the TFs previously characterized (such as FOSL2, STAT3, BHLHB2, and RUNX1), FOSL1 and CEBPB might play a dominant role in the NF1-mediated MES transition that occurs in a glioma cell-intrinsic manner." (PMID 34399888, 2021). "For instance, phosphatase and tensin homolog (PTEN) deficiency in glioma drives macrophage infiltration via up-regulation of lysyl oxidase (LOX) and in mesenchymal GBMs neurofibromin 1 (NF1) deficiency results in increased GAM infiltration compared with proneural or classical subtypes." (PMID 33802571, 2021). "Cre-loxP systems have been utilized to evaluate the relationship between NF1 and glioma formation." (PMID 33806933, 2021).
glioma (continued). "Despite these findings, RNA‐seq from a Nf1;Tp53CKO mouse model of glioma where the tumors also lack ASCL1 revealed that although some Notch related genes (Dll3, Hes5, Hes6) were decreased, expression of many of the Wnt related genes seemed unaffected by the loss of ASCL1." (PMID 32573857, 2020). "From P60‐120, we found that 100% of Nf1;Tp53CKO mice exhibited neurological symptoms and had tumors that evolved into an expanded mass with high mitotic index and microvascular proliferation resembling that of high‐grade gliomas." (PMID 32573857, 2020). "As for target specific therapies, MEK inhibitors have shown promising results in NF1 patients with low grade gliomas, this result may pose the basis for future treatment strategies also in NF1-pHGG." (PMID 33282797, 2020). "Approximately 50% of low-grade NF1-gliomas displayed an immune signature, T lymphocyte infiltration, and increased neo-antigen load, implying that such tumors may also be targeted via immunotherapies." (PMID 31906320, 2020). "Although these mutations occurred in the context of mutant EGFR (implying genetic cooperation), this does not preclude these being drivers in other contexts without EGFR, as exemplified by Pten and Nf1 also causing multiple glioma types with other drivers." (PMID 32727536, 2020). "In contrast, in vivo we found that Ascl1;Nf1;Tp53CKO mice (hence forth referred to as Ascl1CKO tumor mice, N = 39) still developed high‐grade tumors that were phenotypically consistent with high‐grade gliomas." (PMID 32573857, 2020). "Moreover, we demonstrate that NF1-mutant neurons support glioma growth by producing MDK, which activates T cells to produce Ccl4, a cytokine that induces microglia to express a critical glioma growth factor (Ccl5)." (PMID 32358581, 2020). "BRAF = missense in NF1-glioma group, missense and frameshift in LGm6 group." (PMID 31906320, 2020). "In addition, cAMP disruption in NF1 mouse models has been shown to be sufficient to promote glioma formation, demonstrating the role of cAMP in the formation of certain tumors." (PMID 33121128, 2020). "Notably, we showed that re-expression of NF1-LRD similarly reversed cellular invasiveness in several human glioma cell lines, patient-derived GPCs and an orthotopic mouse glioma model." (PMID 30967630, 2019). "Detecting ATRX alterations may also have management implications for NF1 patients with gliomas, since when present they identify subgroups that are clinically more aggressive." (PMID 31462295, 2019). "In addition, another group of aggressive gliomas characterized by a high frequency of ATRX alterations and ALT activation is PA with anaplasia, approximately one third of which are NF1-associated or demonstrate somatic NF1 gene mutations." (PMID 31462295, 2019). "One important finding in our current study is that in NF1-associated gliomas, ALT is independently associated with worse survival in a multivariate model also accounting for grade and age, two key factors consistently associated with survival in gliomas." (PMID 31462295, 2019). "In this study, we demonstrate that the NF1-LRD domain of NF1 plays a role in glioma invasiveness." (PMID 30967630, 2019). "Thus, our findings add ACVR1 to NF1 deletion as an additional genetic alteration found in human gliomas that promote mesenchymal transformation." (PMID 30833574, 2019).
glioma (continued). "Glioma initiation events may also include point mutations in RTK pathway genes such as EGFR and PDGFRA or in MAPK pathway genes such as neurofibromin 1 (NF1)." (PMID 29616301, 2018). "There are prior reports on the differences between sporadic (non-NF-1) gliomas and NF-1 associated gliomas, but only a few evaluated the OCT measurements in these two groups." (PMID 30619059, 2018). "Similar to our study, they found that sporadic gliomas were more likely to cause vision loss than NF-1 associated gliomas, but they did not directly compare the NF-1 and non-NF-1 patients on OCT." (PMID 30619059, 2018). "RAS/MAPK activation in glioma has been shown to result both from constitutive activation of receptor tyrosine kinases EGFR, PDGFRA, and c-MET as well by an inactivating mutation of NF1, a suppressor of RAS GTPase activity." (PMID 28256619, 2017). "Low-grade brain gliomas are a well-recognized complication of NF1 and they may remain indolent over many years; however, a small number of low-grade gliomas transform into more aggressive tumour types." (PMID 28593402, 2017). "These distinct patterns of glioma latency do not reflect differences in the timing or brain location of somatic Nf1 loss." (PMID 28525381, 2017). "Degradation of the NF1 protein, independent of NF1 mutation status, phenocopies inactivating mutations to drive tumors in human glioma cell lines." (PMID 28166733, 2017). "We also acknowledge funding from the Children‘s Tumor Foundation Synodos Low-Grade Glioma Initiative that aims to comprehensively characterize the genetic and genomic changes in NF1-LGG as a means to develop more accurate preclinical models of these common tumors." (PMID 28066715, 2016). "In this subtype, one of the signature genetic changes is mutation of the NF1 tumor suppressor gene, which is intriguing, given the prior identification of ABCG1 as a uniquely upregulated transcript in GSCs originating from a mouse model of low-grade glioma harboring biallelic Nf1 gene inactivation." (PMID 26981778, 2016). "Thus, recurrent loss of chromosomal regions and frequent mutations in PTEN and NF1 strongly contributed to the weak expression and functional loss of NF1-M and PTEN-M in the RMPAhigh glioma subtype." (PMID 27385209, 2016). "Further, 21 and 10 RMPAhigh gliomas harbored heterozygous and homozygous loss of NF1, respectively; 10 additional RMPAhigh gliomas harbored NF1 mutation without loss of NF1 locus." (PMID 27385209, 2016). "No specific mutation of the NF1 gene has been associated with localization of the glioma at the optic chiasm." (PMID 26666878, 2015). "In addition, the pro-proliferative transcription factor CREB was shown to regulate the expression of NF1 and inhibit the migration of glioma cells." (PMID 23185366, 2012). "We confirmed that CREB can positively regulate the expression of NF1 in glioma cells, which might explain the migration-inhibitory role of CREB." (PMID 23185366, 2012). "The experimental evidence regarding the cell of origin of NF1-driven gliomas remains controversial." (PMID 21931722, 2011). "NF1 also represents a major risk factor in the development of several malignancies, particularly malignant peripheral nerve sheath tumours (MPNST), optic gliomas, other gliomas, rhabdomyosarcoma, astrocytoma and neurofibrosarcoma and leukemias." (PMID 20205809, 2010). "Furthermore, it is an orphan drug designation for NF1-altered gliomas." (PMID 41514664, 2026).